HMCN1 (hemicentin 1)
Diseases named in the same sentence as HMCN1 in open-access papers (continued):
Sharing a sentence is not in itself a finding about the gene and the disease.
osteosarcoma (1 paper, 2025). A usually aggressive malignant bone-forming mesenchymal neoplasm, predominantly affecting adolescents and young adults. "Further, prognostic analysis indicated that high HMCN1 expression was significantly associated with poor prognosis in patients with osteosarcoma." (PMID 41458588, 2025). "Analysis using Chronos loss-of-function scores indicated that HMCN1 plays important functional roles in various malignancies, including osteosarcoma." (PMID 41458588, 2025). "The findings in osteosarcoma provide a foundational rationale for developing HMCN1 as a potential therapeutic target." (PMID 41458588, 2025). "Second, although our study confirms the significant role of HMCN1 in osteosarcoma progression, its precise molecular mechanisms require further elucidation." (PMID 41458588, 2025). "These functional gains and losses, coupled with the consistent shifts in EMT marker expression, demonstrate that HMCN1 promotes osteosarcoma cell invasion and migration by regulating the EMT process." (PMID 41458588, 2025). "To functionally validate the role of HMCN1 in driving malignancy via regulation of EMT in osteosarcoma, we conducted a series of in vitro experiments." (PMID 41458588, 2025). "Functional validation in osteosarcoma confirmed that HMCN1 knockdown suppressed, while its overexpression enhanced, cell migration and invasion through regulation of key EMT markers." (PMID 41458588, 2025). "Second, expanding on this, the therapeutic potential of combining such HMCN1-targeting strategies with existing conventional treatments for osteosarcoma should be thoroughly investigated." (PMID 41458588, 2025). "In osteosarcoma in particular, HMCN1 was highly expressed and found to promote malignant phenotypes, and its function as an EMT-associated tumor-promoting gene was validated." (PMID 41458588, 2025). "Transwell migration, invasion, and wound healing assays demonstrated that HMCN1 overexpression significantly enhanced malignant behaviors in osteosarcoma." (PMID 41458588, 2025). "Wound healing and Transwell assay results indicated that knocking down HMCN1 significantly inhibited the migration and invasion capabilities of osteosarcoma cells, whereas its overexpression produced the opposite, promotive effect." (PMID 41458588, 2025). "Next, we investigated the cellular heterogeneity of osteosarcoma and distribution of HMCN1 expression across cell types through single-cell transcriptome sequencing analysis." (PMID 41458588, 2025). "This strongly supporting a potential role for HMCN1 in the EMT process during osteosarcoma progression (as observed from the pan-cancer data analysis)." (PMID 41458588, 2025). "The results revealed that HMCN1 expression was the highest in malignant osteosarcoma cells." (PMID 41458588, 2025). "We experimentally confirmed that HMCN1 promotes osteosarcoma malignancy by regulating EMT." (PMID 41458588, 2025). "We first confirmed that HMCN1 was significantly overexpressed at both the mRNA and protein levels in osteosarcoma cell lines using RT-qPCR and western blot analysis: MG63 and Saos-2 cells showed the most prominent upregulation of HMCN1 in comparison to cells." (PMID 41458588, 2025). "No studies have yet investigated HMCN1 expression in osteosarcoma or its impact on patient prognosis." (PMID 41458588, 2025).
postpartum depression (1 paper, 2018). A type of clinical depression that occurs after childbirth. "Second, HMCN1, which contains estrogen receptor binding site, seems to be associated with postpartum depression symptoms, and one of its functions is suggested to be cell adhesion." (PMID 30279964, 2018).
pulmonary atresia (1 paper, 2025). "The identification of rare variants in the gene HMCN1 in additional patients with pulmonary atresia from the medical literature, supports the study findings." (PMID 39587356, 2025). "Rare variants in HMCN1 (HGNC 19194) were previously reported in association with pulmonary atresia (PA)." (PMID 39587356, 2025). "However, literature review identified rare variants in HMCN1, previously reported as causative for pulmonary atresia, confirming the approach utility." (PMID 39587356, 2025).
renal cell carcinoma (1 paper, 2025). "Studies in breast and renal cell carcinomas suggest HMCN1 mutations may influence energy metabolism and anti-tumor immunity, though these associations await functional validation." (PMID 41479892, 2025).
retinitis pigmentosa (1 paper, 2023). Retinitis pigmentosa (RP) is an inherited retinal dystrophy leading to progressive loss of the photoreceptors and retinal pigment epithelium and resulting in blindness usually after several decades. "HMCN1 is an extracellular matrix protein sharing similarities to fibulins and has been linked to retinitis pigmentosa." (PMID 37628652, 2023).
small-cell gallbladder neuroendocrine carcinoma (1 paper, 2022). "HMCN1 mutation has been found in many cancers such as gastric, colorectal, prostate, triple-negative breast cancer, and small-cell gallbladder neuroendocrine carcinoma." (PMID 35886066, 2022).
stomach adenocarcinoma (1 paper, 2025). "OS analysis indicated that high HMCN1 expression was significantly associated with shortened OS in patients with BLCA, KIRP, MESO, OV, and stomach adenocarcinoma (STAD)." (PMID 41458588, 2025).
uveal melanoma (1 paper, 2025). A melanoma derived from melanocytes of the uveal tract. "The results demonstrated that, except in the case of uveal melanoma, HMCN1 showed a positive correlation with EMT scores in all the other cancer types examined." (PMID 41458588, 2025).
cancer (16 papers, 2014 to 2025). A tumor composed of atypical neoplastic, often pleomorphic cells that invade other tissues. "Through a systematic pan-cancer analysis, this study establishes for the first time that elevated HMCN1 expression is a conserved biomarker positively associated with EMT across cancer types." (PMID 41458588, 2025). "Analysis of SNV data from the TCGA database indicated that HMCN1 exhibits a moderate mutation frequency in several cancers, with the frequency being particularly high in SKCM." (PMID 41458588, 2025). "Our pan-cancer analysis demonstrated a significant association between HMCN1 expression, EMT pathway activity, and higher EMT scores." (PMID 41458588, 2025). "Further analysis based on the cBioPortal database revealed differential mutation frequencies of HMCN1 across various cancer types." (PMID 41458588, 2025). "Mechanistically, the ECM component HMCN1 expression is strongly associated with the pro-metastatic EMT pathway across cancers." (PMID 41458588, 2025). "We first mapped the mutation spectrum of HMCN1 across pan-cancer datasets by color coding the circles corresponding to each mutation type in the plot." (PMID 41458588, 2025). "Overall, these findings demonstrate that HMCN1 holds diagnostic and prognostic value across different cancer types." (PMID 41458588, 2025). "HMCN1 markedly regulate cancer associated fibroblasts migration via the RhoA/ROCK signaling pathway." (PMID 39050894, 2024). "In the future, we will carry out clinical and biological experiments to validate the function and clinical significance of HMCN1 mutation in ccRCC and further explore the underlying mechanisms related to HMCN1 mutation in cancers." (PMID 35886066, 2022). "Since HMCN1 mutation plays an essential role in cancer development, it is necessary to elucidate the underlying mechanisms." (PMID 35886066, 2022). "Mutations and the altered expression of HMCN1 have been proved to be involved in malignant tumor development." (PMID 35886066, 2022). "In line with this, MSC-1 harbored mutations in many drivers, such as ATM, BRAF, and HMCN1, which play vital roles in the tumorigenesis and development of many cancers." (PMID 33959500, 2021). "We also used other 15 types of cancer dataset from TCGA and examined the association between HMCN1 VAFs and OS." (PMID 30279964, 2018). "Furthermore, Spearman correlation analysis revealed a significant positive association between HMCN1 expression levels and various genomic instability scores across multiple cancers." (PMID 41458588, 2025). "Our GSEA results showed that HMCN1 mutation was mainly associated with cellular metabolism-related pathways including glucose and lipid metabolism, which are extremely necessary for tumorigenesis and cancer progression." (PMID 35886066, 2022). "Although the detailed function of HMCN1 remains unknown, it is located in extracellular matrix and the mutation in the gene might be associated with cancer cell invasion and metastasis." (PMID 30279964, 2018). "Although the detailed function of HMCN1 in humans remains unknown, mutations in HMCN1 might be associated with cancer cell invasion and metastasis." (PMID 30279964, 2018). "Furthermore, HMCN1 was also a significant risk factor for worsened DFI in these cancers." (PMID 41458588, 2025). "Therefore, HMCN1 mutations may be associated to cancer proliferation and metastasis because of the disruption of these functions." (PMID 30279964, 2018). "In summary, HMCN1 exhibits an overexpression pattern in various cancer tissues, and its expression is spatially concentrated in malignant areas in a way that is highly consistent with the distribution of tumor cells." (PMID 41458588, 2025). "Nonetheless, this pan-cancer pattern suggests a potential link between HMCN1 expression and a genomic context characterized by higher chromosomal instability." (PMID 41458588, 2025).
cancer (continued). "The extracellular matrix (ECM) critically regulates tumor progression, but the systematic role of its large constituent hemicentin-1 (HMCN1) across cancers remains poorly defined." (PMID 41458588, 2025). "Functionally, knocking down HMCN1 significantly suppressed Transwell invasion of cancer cells, a mechanism shown to be mediated through the activation of the RhoA signaling pathway in fibroblasts." (PMID 41458588, 2025). "We performed an integrative multi-omics analysis of HMCN1 across 33 cancer types using data from TCGA, GTEx, and CPTAC." (PMID 41458588, 2025). "The results showed that in cancers such as BLCA, STAD, KIRP, and PAAD, the effect of HMCN1 expression on survival risk followed a linear trend." (PMID 41458588, 2025). "This suggests that HMCN1 expression is a highly conserved indicator of EMT activity across cancer types." (PMID 41458588, 2025). "While our study has the enormous advantage of a pan-cancer analysis of data from multiple databases and provides valuable insights into the broad role of HMCN1, there are several limitations that need to be acknowledged." (PMID 41458588, 2025). "We delineated the genomic, transcriptomic, and proteomic landscapes of HMCN1 and used the resulting data to evaluate its prognostic value and immunomodulatory functions across cancer types." (PMID 41458588, 2025). "The results consistently demonstrated that HMCN1 is a significant unfavorable prognostic factor in various cancers." (PMID 41458588, 2025). "The results revealed that although HMCN1 protein expression showed an upward trend in most cancer types, this dysregulation was statistically significant only in a few cases." (PMID 41458588, 2025). "Importantly, HMCN1 emerged as a novel regulator of epithelial-mesenchymal transition (EMT) in the cancer milieu." (PMID 41458588, 2025). "However, a critical and unresolved question remains: does HMCN1 act as a conserved, central regulator of cancer progression across diverse tumors, or merely as a context-dependent passenger?" (PMID 41458588, 2025). "Analysis based on protein expression data from The Cancer Proteome Atlas and pathway activity scores revealed that in the vast majority of cancer types, the high HMCN1 expression groups showed significant enrichment in EMT-related pathways, while cell cycle pathway activity was relatively lower." (PMID 41458588, 2025). "The results showed that HMCN1 had significant positive correlations with the infiltration levels of multiple immune cell types as well as stromal cells, such as endothelial cells, across the pan-cancer datasets." (PMID 41458588, 2025). "Therefore, we applied this technology to determine the expression of HMCN1 in specific cell types by analyzing pan-cancer single-cell RNA sequencing data from the TISCH database." (PMID 41458588, 2025). "Critically, it is unknown whether HMCN1 represents a conserved oncogenic driver across cancers or a context-dependent factor, and its potential role as a master regulator of central processes like epithelial-mesenchymal transition (EMT) is poorly defined." (PMID 41458588, 2025). "Furthermore, paired analysis using data from the TCGA pan-cancer dataset consistently demonstrated that HMCN1 mRNA expression was markedly upregulated in most tumor tissues compared to adjacent normal tissues." (PMID 41458588, 2025). "Finally, ROC curve analysis confirmed that HMCN1 has high accuracy in distinguishing tumor from normal tissue and is applicable to most cancer types." (PMID 41458588, 2025). "Thus, HMCN1 could be regarded as a potential combination target for immunotherapy and offers a new direction for pan-cancer immunotherapy strategies." (PMID 41458588, 2025). "When HMCN1 does not function properly in cancer cell, sufficient cell adhesion might be inhibited and as a result of promoting cancer invasion due to instability of HMCN1 caused by the variants in the gene." (PMID 30279964, 2018).
cancer (continued). "To investigate the role of HMCN1 in this process, we further analyzed the correlation between its expression levels and EMT scores across 33 cancers." (PMID 41458588, 2025). "This study identifies HMCN1 as a novel, conserved regulator of EMT and a candidate prognostic biomarker across cancers." (PMID 41458588, 2025). "Collectively, our work elevates HMCN1 from a mere ECM constituent to a key regulatory node and potential therapeutic target within the central ECM–EMT axis of cancer progression." (PMID 41458588, 2025). "This suggests that high HMCN1 expression is associated with malignant tumor progression and is linked to the EMT process rather than directly by driving cell proliferation during cancer advancement." (PMID 41458588, 2025). "Although implicated in cell invasion and migration, a comprehensive pan-cancer understanding of HMCN1 is lacking." (PMID 41458588, 2025). "Additionally, sufficient studies have suggested that SETD2, BAP1, mTOR, MUC16, HMCN1, KDM5C, ARID1A, and PTEN are intimately tied to prognosis and immune response in cancers." (PMID 35936012, 2022). "HOXD9 has been shown to promote cancer development via transcriptional activation of oncogenes, such as RUN and FYVE domain containing 3 (RUFY3), Snail family transcriptional repressor 1 (SNAI1), Sodium channel epithelial 1α subunit (SCNN1A) and Hemicentin 1 (HMCN1)." (PMID 36907878, 2023).
tumor (14 papers, 2017 to 2025). "Using data from the TCGA database, we first assessed the association between HMCN1 expression and tumor status using univariate logistic regression analysis." (PMID 41458588, 2025). "This indicates that elevated HMCN1 expression is significantly associated with the tumor state, reflecting its differential expression between malignant and normal tissues." (PMID 41458588, 2025). "HMCN1 is mutated and aberrantly expressed in a variety of tumors, and, in ccRCC, HMCN1 mutations are a key event in tumor progression." (PMID 37215130, 2023). "To this end, we also carried out comprehensive analyses to find out the novel pathways in HMCN1-mutant samples and elucidated that the potential mechanisms of HMCN1 mutation were related to cellular metabolism and anti-tumor immunity in ccRCC development." (PMID 35886066, 2022). "We found tumor size (P = 0.028) and molecular subtype (P = 0.021) were related with the HMCN1 mutation." (PMID 30279964, 2018). "In the current study, we found that CA9, the expression of which is also associated with tumor hypoxia, was expressed at significantly higher levels in patients with higher HMCN1 VAFs than in those with lower VAFs." (PMID 30279964, 2018). "Furthermore, in bovine leukemia virus infection models, HMCN1 upregulation was associated with tumor cell migration." (PMID 41458588, 2025). "While CUL3 mutations may compromise its tumor-suppressor function and promote progression, the roles of HMCN1 and TBX3 are less defined." (PMID 41479892, 2025). "The correlation of HMCN1 mutation and tumor immunity was also evaluated." (PMID 35886066, 2022). "In terms of immune cell infiltration conditions, naive CD4T and follicular helper T (Tfh) cells show significantly different abundance in HMCN1 mutant samples, indicating that HMCN1 mutation may enhance anti-tumor immune responses." (PMID 35886066, 2022). "HMCN1 mutation was considered as an independent prognostic biomarker and may be relevant to cell metabolism and anti-tumor immunity." (PMID 35886066, 2022). "Since our previous results have suggested that HMCN1 mutation can affect metabolic pathways, it may be important to further explore the correlation between HMCN1 mutation and anti-tumor immunity regulated by cellular metabolism." (PMID 35886066, 2022). "HMCN1 mutation was also correlated with anti-tumor immunity." (PMID 35886066, 2022). "recently reported that the HMCN1 mutations are frequently detected in patients with ccRCC and are correlated with a higher tumor mutation burden and dismal clinical consequences, and may correlate with anti-tumor immunity and cell metabolism." (PMID 36353536, 2022). "Next, the mRNA expression level of HMCN1 was compared between various tumor tissues and corresponding normal tissues using data from the TCGA and GTEx databases." (PMID 41458588, 2025). "The results showed that HMCN1 is primarily expressed in fibroblasts, endothelial cells, and a subset of tumor cells." (PMID 41458588, 2025). "First, the anti-tumor efficacy of the identified candidate, arachidonyltrifluoromethane, requires functional validation in vitro to directly assess its ability to inhibit HMCN1-mediated oncogenic phenotypes." (PMID 41458588, 2025). "HMCN1-high tumors were enriched in inflammatory immune subtypes and exhibited a dysfunctional tumor microenvironment." (PMID 41458588, 2025). "Based on this, we employed multiple algorithms to further evaluate the correlation between HMCN1 and the abundance of various cell types in the tumor microenvironment." (PMID 41458588, 2025). "Besides, Tfh cells were most relevant to CD8T cells and exhibited the highest negative association with M2 macrophages, further confirming the hypothesis that an altered tumor immune microenvironment induced by HMCN1 mutation may be involved in enhancing anti-tumor immunity." (PMID 35886066, 2022).